NOTCH1 (notch receptor 1)
Diseases named in the same sentence as NOTCH1 in open-access papers (continued):
Sharing a sentence is not in itself a finding about the gene and the disease.
diabetic nephropathy (17 papers, 2017 to 2025). "Several studies have confirmed the association between the increased Notch 1, 3, and 4 expressions in renal tissue and the development of diabetic nephropathy." (PMID 36294921, 2022). "Inhibition of GH-induced Notch1 signaling may be a promising strategy for preventing diabetic nephropathy, a common cause of NS in the adult population." (PMID 39200324, 2024). "In diabetic nephropathy, high concentrations of glucose promote fibrosis through the Notch1 pathway." (PMID 40822939, 2025). "Researchers have discovered that excess GH induces Notch1 signaling in podocytes, contributing to proteinuria in diabetic nephropathy." (PMID 40246828, 2025). "Numb is downregulated in diabetic nephropathy tissues and high glucose-stimulated endothelial cells, while Notch1 and Hes1 are upregulated." (PMID 40822939, 2025). "GH induces Notch1 signaling in podocytes, a pathway that generally participates in the development and homeostasis of various organs and contributes to proteinuria in diabetic nephropathy." (PMID 39200324, 2024). "In diabetic nephropathy, ectopic activation of the Notch1 pathway drove macrophage differentiation into a pro-inflammatory M1 subtype." (PMID 37622120, 2023). "Increased renal Notch signaling is detected in the patients with diabetic nephropathy, as evidenced by increased expression of cleaved Notch1." (PMID 31690016, 2019). "This study explored the changes in expression of vascular smooth muscle cell (VSMC) markers and osteogenic markers, as well as the involvement of Notch1-RBP-Jk/Msx2 pathway in a rat model of diabetic nephropathy (DN) with vascular calcification." (PMID 29464183, 2017). "Abnormal activation of the Notch1 signaling pathway may affect the therapeutic effect of islet transplantation in diabetic nephropathy by changing the balance of podocyte apoptosis and autophagy." (PMID 40822939, 2025). "C-peptide also inhibits the activation of Notch1 and Jagged1 in the Notch signaling pathway and TGF-β1 in the TGF-β signaling pathway, thereby alleviating the progression of diabetic nephropathy." (PMID 40822939, 2025). "In this paper, Wnt signaling pathway, Notch-1 signaling pathway and abnormal regulation of HDAC4 and miR-29a all play an important role in podocyte injury in diabetes nephropathy." (PMID 40862124, 2025). "Although Notch1 is seldom expressed in the kidneys of healthy adults, the re-expression and activation of Notch1 are found in podocytes and tubular cells of patients diagnosed with kidney diseases, indicating that its activation may be essential for the progression of diabetic nephropathy." (PMID 39598328, 2024). "In addition, EGCG treatment can significantly reduce the levels of Notch1 and TGF-βRII in HEK293 cells stimulated by high glucose, further supporting the potential of EGCG in the treatment of diabetic nephropathy." (PMID 40822939, 2025). "Indeed, conditional deletion of Notch1, but not Notch2, in podocytes of mice with diabetic nephropathy abrogates glomerulosclerosis." (PMID 29398135, 2018).
diffuse large B-cell lymphoma (17 papers, 2013 to 2025). "Mutations in NOTCH1 have been reported in a minor subset of diffuse large B cell lymphoma." (PMID 23825651, 2013). "Investigate the role of the Neurogenic locus notch homolog protein 1 (NOTCH1) signaling pathway in Diffuse large B-cell lymphoma (DLBCL)-related heart pathogenesis." (PMID 39951437, 2025). "Mirroring the results in the Notch-1 animal model, analysis of gene-expression by diffuse large B-cell lymphomas showed the presence of activated Notch-1 signalling which correlated with increased levels of IL-33 and Treg gene signatures." (PMID 35350071, 2022). "Furthermore, Notch1 mutations were found in diffuse large B-cell lymphoma (DLBCL), splenic marginal zone lymphoma (SMZL), Hadju-Cheney syndrome, breast cancer, and in 12% of non-small-cell lung carcinomas (NSCLCs), of which half were in the PEST domain." (PMID 28149836, 2016). "In typically MYC-driven Burkitt lymphoma, 7% (5/70) carry Notch1 mutations, 8% (5/63) of BCL2-associated diffuse large B-cell lymphoma (DLBCL) carry similar PEST mutations of Notch2, and 6% (2/35) had amplification of the Notch2 locus." (PMID 24959528, 2014). "Thus, NOTCH1 activation is uncommon in diffuse large B cell lymphoma." (PMID 23825651, 2013). "Moreover, studies suggest a strong association between NOTCH1 mutations and an increased risk of Richter’s transformation, the progression of CLL into aggressive diffuse large B-cell lymphoma (DLBCL), which significantly worsens patient prognosis." (PMID 40277842, 2025). "Specifically, activating NOTCH2 mutations have been identified in marginal zone B-cell lymphoma and diffuse large B-cell lymphoma, and biochemical analyses have detected activation of NOTCH2 as well as NOTCH1 in CLL." (PMID 23825651, 2013). "An unexpected finding, based on prior results of genomic sequencing studies, was the much more widespread activation of NOTCH1 in CLL than in other two other B cell tumors, mantle cell lymphoma and diffuse large B cell lymphoma." (PMID 23825651, 2013). "Additionally, genomic mutations are also implicated in this process, supported by identified mutations in Neurogenic Locus Notch Homolog Protein (NOTCH) 2, NOTCH1, and Phosphatase and Tensin Homolog (PTEN) in HCV-positive diffuse large B cell lymphoma (DLBCL) patients." (PMID 38654358, 2024). "Genetic alterations in Notch genes, mainly in Notch1 and Notch2, occur in other B-cell malignancies such as CLL, splenic marginal zone lymphoma, mantle cell lymphoma diffuse large B-cell lymphoma (DLBCL) and, rarely, follicular lymphoma." (PMID 31346528, 2019).
metastatic tumors (17 papers, 2012 to 2025). "Activating NOTCH1 mutations are reported in ∼ 20% of cases with recurrent and/or metastatic disease, and are associated with a more aggressive disease phenotype and poor overall survival (OS) as compared to patients with wild-type NOTCH1." (PMID 39794830, 2025). "Three new somatic mutations, including ERBB3, DNMT3A and NOTCH1 mutations were detected in the metastatic tumor." (PMID 30850667, 2019). "In ACC, NOTCH1 mutations have been shown to be enriched in recurrent and metastatic tumors and mutations in NOTCH pathway genes characterize a small subset of cases with solid histology and a particularly aggressive clinical course." (PMID 29731974, 2018). "Tissue samples of localized and metastatic tumors were divided into three groups based on their tumor stages and the relative mRNA expression of Notch1 and Jagged1 were analyzed." (PMID 22506064, 2012). "Notch1 expression was elevated in all stages in metastatic tumors compared to localized tumors but the difference was significant in T1 stage only (P = 0.001)." (PMID 22506064, 2012). "The average size of metastatic tumors was significantly larger than localized tumors in T1 stage ccRCC and the elevated expression of Notch1 was significantly positive correlated with the tumor diameter." (PMID 22506064, 2012). "NOTCH1 is significantly elevated in highly metastatic PCa cell lines, metastatic human prostate tissue, malignant prostate epithelial cells from primary and metastatic tumors in transgenic mouse models of PCa, and bone metastases from human PCa." (PMID 38538986, 2024). "Dysregulation of Notch signaling leads to various types of cancer in different tissues, such as breast cancer, gastric cancer, and pancreatic cancer, and elevated Notch1 expression has been observed in malignant prostatic epithelial cells of primary and metastatic tumors." (PMID 38538986, 2024). "Because of the function of Jagged1 which could enable the metastasis of ccRCC, it is hard to understand the difference between Jagged1 and Notch1 such as relative lower expression of Jagged1 in metastatic tumors compared to localized tumors." (PMID 22506064, 2012). "NOTCH1 expression is significantly elevated in metastatic tumors in T1 stage, with tumor size positively correlating with the elevated expression levels and the average size of metastatic tumors being significantly larger non-metastatic tumors in T1 stage of clear cell renal cell carcinoma." (PMID 31690016, 2019). "Compared to localized tumors, Notch1 expression was significantly elevated in metastatic tumors in T1 stage only while Jagged1 expression was not statistically different among all stages indicating that only the receptor Notch1 was associated with the metastasis of ccRCC at T1 stage." (PMID 22506064, 2012). "Of newly diagnosed CRC patients, 40–50% will develop metastasis; based on the evidence that Notch1 promotes tumorigenesis and the spread of metastatic disease in CRC, targeting Notch1 signaling gains momentum for the treatment of CRC." (PMID 32630477, 2020). "The expression level upregulation of the genes might be mediated by TFs, such as POLR3D, NOTCH1 and ETS1, which were widely expressed at high levels in bone metastatic tumor samples." (PMID 38462627, 2024). "Furthermore, significantly higher nuclear expression of Notch1, -3 and -4, HES-1, and HEY-1 (all p≤0.001) was noted in locally advanced and metastatic tumours compared to resectable cancers." (PMID 23226563, 2012). "Compared to non-tumor tissues, Notch1 and Jagged1 expression were significantly elevated both in mRNA and protein levels in localized and metastatic tumors which was consistent with some other reports." (PMID 22506064, 2012).
metastatic tumors (continued). "First, we studied the basic expression level of Notch1 and Jagged1 in 25 metastatic tumors, 26 localized tumors and adjacent non-tumorous kidney tissue counterparts." (PMID 22506064, 2012). "In order to determine the expression level of Notch1 and Jagged1, 51 ccRCC samples including 25 metastatic tumor samples, 26 localized tumor samples and adjacent non-tumorous kidney tissue counterparts were used for real-time RT-PCR and Western-blot." (PMID 22506064, 2012). "Compared to localized tumors, Notch1 expression was significantly elevated in metastatic tumors in T1 stage while Jagged1 expression was not statistically different between localized and metastatic tumors of all stages." (PMID 22506064, 2012). "Similar to the mRNA expression level, elevated expression of Notch1 and Jagged1 protein was observed in tumor tissues compared to non-tumor tissues and higher and lower expression of Notch1 and Jagged1 were detected respectively in metastatic tumors compared to localized tumors." (PMID 22506064, 2012).
pulmonary fibrosis (17 papers, 2016 to 2025). Chronic progressive interstitial lung disorder characterized by the replacement of the lung tissue by connective tissue, leading to progressive dyspnea, respiratory failure, or right heart failure. "Notch1, an important regulator of cell differentiation and proliferation, is also associated with the cellular processes involved in myofibroblast differentiation and its inhibition would, therefore, alleviates skin, kidney and lung fibrosis." (PMID 35355403, 2022). "Clinically, Rho-kinase activity is increased in lung tissue from patients with IPF and is thought to lead to Notch1-mediated lung fibrosis." (PMID 37626755, 2023). "Enhanced Notch signaling was discovered during pulmonary fibrosis development, while the suppression of JAG1, Notch1, NICD, and Hes-1 neutralized the development of bleomycin-induced pulmonary fibrosis." (PMID 36499287, 2022). "Notch1 signaling in response to HIMF plays a significant role in myofibroblast differentiation during lung fibrosis." (PMID 34336840, 2021). "Another study showed that Notch 1 inhibition with DAPT attenuated lung fibrosis in the bleomycin mouse model, decreased α-SMA and Col I, and downregulated PDGFRβ and ROCK1 expression." (PMID 34691383, 2021). "Lung tissues from patients with pulmonary fibrosis were examined for the expression of Notch1/PDGFRβ/ROCK1 using RT-qPCR, western blotting, and immunostaining." (PMID 30902967, 2019). "All of these studies have shown the involvement of Notch1 and its downstream signaling pathway in the development of pulmonary fibrosis, suggesting the potency of using these molecules as the targets for potential drug intervention." (PMID 30902967, 2019). "In this study, we performed both in vitro and in vivo studies to examine the effect of Notch1 and its related signaling pathway in the pathogenesis of pulmonary fibrosis." (PMID 30902967, 2019). "Our results showed that the Notch1 inhibitor effectively alleviated pulmonary fibrosis, as supported by an improved histological phenotype and decreased PMT activity." (PMID 30902967, 2019). "With a mouse model, we further showed that a Notch1 inhibitor alleviated lung fibrosis, thus providing a potential treatment strategy for human IPF." (PMID 30902967, 2019). "To substantiate the effect of the Notch1/PDGFRβ/ROCK1 axis on pericyte differentiation and pulmonary fibrosis, we generated a mouse pulmonary fibrosis model in which the Notch1 signaling pathway inhibitor DAPT was used as a treatment." (PMID 30902967, 2019). "The goals of this study were to investigate the role of the Notch1/PDGFRβ/ROCK1 signaling pathway in the pathogenesis of pulmonary fibrosis and to explore the possibility of treating fibrosis by targeting Notch1." (PMID 30902967, 2019). "After illustrating the molecular pathway of Notch1 in mediating pericyte proliferation and cell behavior in vitro, we further tested the effect of Notch1 on the pathogenesis of pulmonary fibrosis with a mouse model." (PMID 30902967, 2019). "As the downstream effector of Notch1, the level of PDGFRβ has been shown to be potentiated in a mouse lung fibrosis model." (PMID 30902967, 2019). "As further substantiation, the administration of a Notch1 inhibitor in a mouse model of lung fibrosis inhibited the PDGFRβ/ROCK1 pathway, suppressed pericyte proliferation and differentiation, and alleviated the severity of fibrosis." (PMID 30902967, 2019). "Notch signaling has been linked to fibrotic diseases, examples of which include Notch1 promotion of differentiation in murine lung fibroblasts and induction of epithelial–mesenchymal transition with increased migratory behavior in pulmonary fibrosis." (PMID 27248323, 2016). "Zhou found that Astragalus injection exerted protective effects on bleomycin-induced pulmonary fibrosis via downregulating Jagged1/Notch1 in lung." (PMID 27143988, 2016).
pulmonary fibrosis (continued). "In a rat model of bleomycin-induced pulmonary fibrosis, the Jagged 1/Notch1 signaling pathway has been observed to induce alpha-smooth muscle actin (α-SMA) expression via NF-κB activation, promoting endothelial mesenchymal transition (EndMT) and accelerating fibrosis." (PMID 39450276, 2024). "Notch1 is a key transcription factor in regulation of lung fibrosis." (PMID 36635762, 2023). "For example, in bleomycin-induced mouse lung fibrosis, Notch 1 and Jagged 1 are highly expressed in fibrotic lungs compared to control normal lungs, and mesenchymal Notch 1 conditional genetic deletion partially diminished bleomycin-induced lung fibrosis and reduced myofibroblast differentiation." (PMID 34691383, 2021). "Our results showed that the Notch1 signaling pathway was aberrantly activated in pulmonary fibrosis, and this pathway may facilitate disease progression via mediating pericyte proliferation and differentiation." (PMID 30902967, 2019). "Using HE staining, we found that tissues in the pulmonary fibrosis (PF) model presented with prominent tissue fibrosis, and this could be partially alleviated by the Notch1 inhibitor." (PMID 30902967, 2019). "The inhibition of the Notch1 pathway may provide one promising treatment strategy for pulmonary fibrosis." (PMID 30902967, 2019). "Finally, a mouse pulmonary fibrosis model was prepared, and a Notch1 inhibitor was administered to observe tissue morphology and pericyte cell behaviors." (PMID 30902967, 2019). "Based on this information and the obtained promising results for the Notch1 inhibitor in mouse pulmonary fibrosis, we thus proposed that the Notch1 inhibitor may work as a potent drug candidate in treating IPF." (PMID 30902967, 2019). "They conclude that Notch1 signaling is activated in pulmonary fibrosis." (PMID 30902967, 2019). "Moreover, we reported for the first time the effectiveness of the Notch1 inhibitor in alleviating mouse lung fibrosis via suppressing pericyte proliferation and transition." (PMID 30902967, 2019). "Therefore, elucidating changes in Notch 1 and Notch 4 signaling pathways in lung fibrosis, and their correlation with EndoMT, is crucial for halting further abnormal transdifferentiation and fibrotic lung disease progression, while preserving normal tissue remodeling." (PMID 39450276, 2024). "In a separate investigation, researchers discovered activation of the Jagged 1/Notch 1 signaling pathway in pulmonary microvascular endothelial cells (PMVECs), promoting EndMT, a process playing multiple significant roles in the pathogenesis of pulmonary fibrosis." (PMID 39450276, 2024). "Interestingly, subsequent studies identified that both the bleomycin-induced mice pulmonary fibrosis and lung specimens from patients with IPF upregulated the known Notch-related genes and mesenchymal-specific conditional Notch1-deficient mice reduced bleomycin-induced pulmonary fibrosis." (PMID 35039472, 2022). "A cell membrane protein called Notch1, which binds to signaling molecules outside cells and then alters the activity of genes inside the cells, might be a promising target for drugs to treat the lung damage of pulmonary fibrosis." (PMID 30902967, 2019). "Another study was designed to investigate the antifibrosis effects and possible mechanism of AR injection on bleomycin-induced pulmonary fibrosis in rats and revealed that AR injection could exert protective effects on bleomycin-induced pulmonary fibrosis via downregulating TGF-β1/Notch1 in lung." (PMID 30909474, 2019). "Mechanistically, SNHG17 can stabilize PTBP1 expression through binding to its 3′UTR, whereas the activated PTBP1 can bind with the NICD part of Notch1 to upregulate Notch1 expression and aggravated EMT and lung fibrosis post radiation." (PMID 36635762, 2023). "Recently, Notch1 has been shown to be involved in myofibroblast activation and to regulate α-SMA expression in lung fibrosis." (PMID 29304760, 2018).
pulmonary fibrosis (continued). "Studies have revealed that in bleomycin-induced pulmonary fibrosis, mice lacking Notch1 exhibit reduced levels of myofibroblasts and collagen I in the lung compared to controls." (PMID 39450276, 2024). "Hence, Notch1 plays a pivotal role in EMT, myofibroblast differentiation, and collagen fiber formation during pulmonary fibrosis pathogenesis." (PMID 39450276, 2024). "Moreover, SNHG17 is an lncRNA that promotes radiation-induced EMT and lung fibrosis through stabilizing PTBP1 expression and activating Notch1 expression." (PMID 36635762, 2023). "Moreover, inhibition of Notch1 using DAPT impedes the conversion of fibroblasts to myofibroblasts, resulting in the downregulation of vimentin and α-SMA protein expression, thereby impeding the progression of pulmonary fibrosis." (PMID 39450276, 2024).